PLIN3 (perilipin 3)
Diseases named in the same sentence as PLIN3 in open-access papers (continued):
Sharing a sentence is not in itself a finding about the gene and the disease.
sarcoma (2 papers, 2020 to 2025). A usually aggressive malignant neoplasm of the soft tissue or bone. "Validation using the public Gene Expression Profiling Interactive Analysis 2 sarcoma dataset confirmed consistent PLIN3 upregulation, and down-regulation of DGAT2 and CIDEC in tumor samples, mirroring our GbPDTO findings." (PMID 41376821, 2025). "Kruskal-Wallis test analysis found that the expressions of PLIN2 (P<0.001), PLIN3 (P<0.001) and PLIN5 (P = 0.013) had a significant difference in various non-lipomatous sarcomas, except for epithelioid sarcomas." (PMID 32368290, 2020). "PLIN2, PLIN3 and PLIN5 expressions were significantly different among non-lipomatous sarcoma (all P<0.01)." (PMID 32368290, 2020). "However, due to the small sample size of epithelioid sarcomas, we analyzed the expression of perilipins in the remaining six sarcomas and found that PLIN2, PLIN3 and PLIN5 showed different and rich expressions in non-lipomatous sarcomas, especially high-grade sarcoma." (PMID 32368290, 2020).
Type 2 Diabetes (2 papers, 2015 to 2021). "In accordance with a recent observation in myotubes from obese individuals with or without type 2 diabetes, we could not detect any change in expressions of PLIN2 and PLIN3, and further investigation on how PLINs and lipases interact is needed." (PMID 25790476, 2015).
amyloidosis (1 paper, 2025). A disorder characterized by the localized or diffuse accumulation of amyloid protein in various anatomic sites. "In the SMC-calc vs. SMC comparison based on limma, clusters related to high-density lipoprotein (HDL) assembly (PF4V1, APOA1, LPXN, AFP, A2M, and MMP1) and amyloidosis (CX3CL1, APOE, PLIN3, TGFBI, and CH25H) were identified." (PMID 41301179, 2025).
Aortic dissection (1 paper, 2025). Aortic dissection refers to a tear in the intimal layer of the aorta causing a separation between the intima and the medial layers of the aorta. "The discovery of PLIN2 and PLIN3 as central modulators of lipid metabolism in aortic dissection highlights their potential as both diagnostic biomarkers and intervention targets." (PMID 41246346, 2025).
dermatofibrosarcoma protuberans (1 paper, 2020). Dermatofibrosarcoma protuberans (DFSP) is a rare infiltrating soft tissue sarcoma, generally of low grade malignancy, arising from the dermis of the skin and characteristically associated with a specific chromosomal translocation t(17;22). "PLIN3 expression was seen in all epithelioid sarcomas (8/8), in most dermatofibrosarcoma protuberans (31/38), undifferentiated sarcomas (25/34), fibrosarcomas (16/18), Ewing's sarcomas (11/17), and in a few rhabdomyosarcomas (5/22) and leiomyosarcomas (12/42)." (PMID 32368290, 2020). "PLIN2, PLIN3 and PLIN5 were widely expressed in liposarcomas, rhabdomyosarcomas, leiomyosarcomas, dermatofibrosarcoma protuberans, undifferentiated sarcomas, fibrosarcomas, Ewing's sarcomas and epithelioid sarcomas." (PMID 32368290, 2020).
gastric carcinoma (1 paper, 2025). A carcinoma that arises from epithelial cells of the stomach. "For instance, high expression of PLIN3 and EPHB2 is associated with macrophage infiltration and poor response to immunotherapy in gastric carcinoma and other solid tumors." (PMID 41188771, 2025).
HIV-1 infection (1 paper, 2025). The type species of lentivirus and the etiologic agent of acquired immunodeficiency syndrome (AIDS). "Despite the increase in mRNA levels, the level of PLIN3 protein was significantly decreased by HIV-1 infection." (PMID 41085277, 2025). "HIV-1 infection increased PLIN3 mRNA level and nuclear accumulation but decreased PLIN3 protein expression in primary CD4+ T cells." (PMID 41085277, 2025). "HIV-1 infection increased PLIN3 m6A methylation and resulted in an upregulation of total PLIN3 mRNA levels." (PMID 41085277, 2025). "Using m6A-specific RNA sequencing, we identified several cellular mRNAs with altered m6A modifications during HIV-1 infection, including PLIN3." (PMID 41085277, 2025). "Future studies will focus on the role of PLIN3 in HIV-1 Env incorporation to better understand how PLIN3 regulates HIV-1 infection in primary CD4+ T cells." (PMID 41085277, 2025). "Polysome profiling revealed that PLIN3 mRNA was less actively translated during HIV-1 infection of primary CD4+ T cells." (PMID 41085277, 2025). "The current study is the first to reveal the effects of HIV-1 infection on PLIN3 mRNA methylation and expression levels in primary CD4+ T cells." (PMID 41085277, 2025). "Our results highlight the importance of m6A RNA modification during HIV-1 infection and suggest PLIN3 as a regulatory protein of HIV-1 replication in primary CD4+ T cells." (PMID 41085277, 2025). "Our findings show the importance of m6A RNA modification in HIV-1 infection by regulating host genes like PLIN3 and suggest a unique regulatory mechanism in HIV-1-infected primary CD4+ T cells." (PMID 41085277, 2025). "We chose to focus further on m6A modification of PLIN3 mRNA during HIV-1 infection of primary CD4+ T cells." (PMID 41085277, 2025). "We further demonstrate that HIV-1 infection regulates PLIN3 mRNA and protein levels, and knocking down PLIN3 reduces HIV-1 release but enhances virion infectivity in primary CD4+ T cells." (PMID 41085277, 2025). "Based on our findings that HIV-1 infection promotes m6A methylation of PLIN3 mRNA in CD4+ T cells, we asked whether infection also changes PLIN3 expression in Jurkat CD4+ T cells." (PMID 41085277, 2025). "We next sought to determine whether HIV-1 infection alters the RNA or protein levels of PLIN3 in primary CD4+ T cells." (PMID 41085277, 2025). "Several previous studies explored the function of PLIN3 during HIV-1 infection." (PMID 41085277, 2025). "We next sought to determine whether HIV-1 infection influences the nucleocytoplasmic localization of PLIN3 mRNA." (PMID 41085277, 2025). "Interestingly, PLIN3 mRNA accumulated more in the nucleus during HIV-1 infection of primary CD4+ T cells compared with mock controls, whereas the levels of PLIN3 mRNA in the cytoplasm were not significantly different." (PMID 41085277, 2025). "Interestingly, HIV-1 infection increased PLIN3 mRNA levels and nuclear localization but reduced PLIN3 protein expression in primary CD4+ T cells." (PMID 41085277, 2025). "Immunoblotting showed that the level of PLIN3 was significantly decreased by HIV-1 infection." (PMID 41085277, 2025). "In contrast, the levels of PLIN3 mRNA were increased by HIV-1 infection." (PMID 41085277, 2025). "We next sought to investigate whether PLIN3 is necessary for HIV-1 infection in primary CD4+ T cells." (PMID 41085277, 2025). "Likewise, PLIN3 protein levels remain unchanged after HIV-1 infection of Jurkat cells." (PMID 41085277, 2025). "We therefore sought to determine whether HIV-1 infection reduces the translation of PLIN3 mRNA." (PMID 41085277, 2025). "HIV-1 infection of primary CD4+ T cells increases the m6A levels and nuclear accumulation of PLIN3 mRNA but decreases translation of the message in the cytoplasm." (PMID 41085277, 2025). "Overall, our results demonstrate that HIV-1 infection does not alter the RNA or protein levels of PLIN3, and PLIN3 KO does not change HIV-1 infection in Jurkat CD4+ T cells." (PMID 41085277, 2025).
HIV-1 infection (continued). "We found that HIV-1 infection did not change the steady-state level of PLIN3 mRNA in Jurkat cells." (PMID 41085277, 2025). "However, whether PLIN3 plays a role in HIV-1 infection of primary CD4+ T cells has not been reported." (PMID 41085277, 2025).
leukemia (1 paper, 2024). A malignant (clonal) hematologic disorder, involving hematopoietic stem cells and characterized by the presence of primitive or atypical myeloid or lymphoid cells in the bone marrow and the blood. "Most of the protein hits could be identified in blood samples according to the HPA database; two of them, namely DPEP1 and SOST, were classified by HPA as upregulated in BC; and five of them were found to be upregulated in leukemia and myeloma: SOST, TXNRD1, PKLR, EPHA2, PLIN3." (PMID 38791048, 2024).
liposarcoma (1 paper, 2020). A usually painless malignant tumor that arises from adipose tissue. "In various types of liposarcoma, the poorer the differentiation was, the higher the degree of malignancy and the higher the expression of the PLIN3 protein would be, except in ML." (PMID 32368290, 2020). "Except for PLIN3, the expression of the other four perilipin members in liposarcoma was pairwise related." (PMID 32368290, 2020). "By analyzing the correlation of perilipin family proteins expressions in liposarcoma, we found that apart from PLIN3, the other four proteins' expression had significant correlations with each other." (PMID 32368290, 2020). "This may indicate that PLIN3 might play a different role with the other four molecules in the development of liposarcoma." (PMID 32368290, 2020). "However, the expression rate of PLIN3 (P=0.002) was obviously increased in liposarcoma." (PMID 32368290, 2020). "The expression levels of PLIN1 (P<0.001), PLIN2 (P<0.05), PLIN3 (P<0.05), and PLIN5 (P<0.001) were closely related to the histological type of liposarcoma." (PMID 32368290, 2020). "The expression rates of PLIN1 (P<0.001), PLIN2 (P=0.034), and PLIN4 (P<0.001) were significantly different in subtypes of liposarcoma, while the expression rates of PLIN3 (P=0.25) and PLIN5 (P=0.051) were not significantly different." (PMID 32368290, 2020).
lymph node metastasis (1 paper, 2024). "Moreover, lymph node metastasis (yes vs no, HR 2.403, 95% CI 1.149–5.026, P < 0.05) and PLIN3 in fibroblasts (high vs low, HR 2.615, 95% CI 1.260–5.428, P < 0.05) could be used as independent prognostic factors for OS and DFS of OSCC in the multivariable models." (PMID 38554152, 2024).
mastitis (1 paper, 2024). Inflammation of breast tissue during lactation or postpartum due to an obstructed duct or infection. "The targeted genes, PLIN3, EDEM2, SURF4, and LGALS9, with mutations/variations have led to metabolic diseases, bovine osteoporosis, mastitis resistance and bovine respiratory disease, respectively." (PMID 38674383, 2024).
neuroblastoma (1 paper, 2021). Neuroblastoma (NB) is the most common solid, extracranial childhood tumor. "Instead, the fact that endogenous αSyn and PLIN3 proteins co-localized at the LD surface in human neuroblastoma cells, suggests that LD-associated αSyn have a direct physiological function in promoting neutral lipid accumulation by inhibiting lipolysis." (PMID 34788284, 2021). "Taken together, these experiments show that αSyn co-localizes at the LD surface with the LD-binding protein dPlin2::GFP in Drosophila photoreceptor neurons and with PLIN3 in human neuroblastoma cells." (PMID 34788284, 2021).
neuroendocrine carcinoma (1 paper, 2025). A malignant neuroendocrine neoplasm composed of cells containing secretory granules that stain positive for NSE and chromogranin. "Importantly, identified compounds (e.g., clofibrate targeting PLIN3) suggest actionable strategies for modulating the TME in neuroendocrine carcinomas." (PMID 41220948, 2025).
non-alcoholic steatohepatitis (1 paper, 2014). "In the liver, Perilipin 2 (Plin2) is the most abundant lipid droplet protein; while Perilipin 3 (Plin3) is mildly expressed and Perilipin 1 (Plin1) is de novo expressed in non-alcoholic steatohepatitis." (PMID 24831094, 2014).
oral squamous cell carcinoma (1 paper, 2024). "Since cancer patients show dysregulated lipid metabolism, we aimed to elaborate the role of LDs-related PLIN3 in oral squamous cell carcinoma (OSCC)." (PMID 38554152, 2024).
osteosarcoma (1 paper, 2022). A usually aggressive malignant bone-forming mesenchymal neoplasm, predominantly affecting adolescents and young adults. "Lipid droplets, PLIN2, and PLIN3 were detected in osteosarcoma tissue samples as well as in 2D and 3D cultivated D-17 and COS4288 cells." (PMID 35834072, 2022). "Lipid droplet coating proteins of the perilipin family (PLIN2, PLIN3) were detected in both, tumor samples and canine osteosarcoma cell lines D-17 and COS4288 as well." (PMID 35834072, 2022).
pyometra (1 paper, 2022). "In our analyses, PLIN2 and PLIN3 were more abundant in pyometra-affected endometrium samples compared to healthy ones." (PMID 35689217, 2022). "PLIN3 expression was also higher in pyometra samples compared to healthy endometrium." (PMID 35689217, 2022).
serous carcinoma (1 paper, 2017). "DPP9 was found rearranged with PLIN3 in another serous carcinoma, and also in this case the DPP9 expression was disrupted and lowered toward the 3′ end." (PMID 28893231, 2017).
triple-negative breast carcinoma (1 paper, 2024). An invasive breast carcinoma which is negative for expression of estrogen receptor (ER), progesterone receptor (PR), and human epidermal growth factor receptor 2 (HER2). "Noteworthy, CD4/CD8 ratio < 1 at the tumor–host interface has prognostic value in triple-negative breast cancer; we likewise found the mean CD4/CD8 ratio to be at 0.47, which was less than 1 and negatively associated with PLIN3, indicating that patients with PLIN3high tumor had a poor outcome." (PMID 38554152, 2024).
tumor (18 papers, 2015 to 2025). "We found that PLIN3 was inversely associated with CD4/CD8 in tumor tissue and knocking-down PLIN3 can reduce intracellular LDs deposits, which was consistent with the previous findings, making us turn to investigate immune checkpoint molecules." (PMID 38554152, 2024). "In this work, immunohistochemistry (IHC) staining of OSCC and single-cell RNA sequencing (scRNA-seq) in head and neck squamous cell cancer (HNSCC) tissue show the location of PLIN3 in tumor." (PMID 38554152, 2024). "Given that PLIN3 promoted B7-H2 protein expression, we reasoned that B7-H2 was required for PLIN3-mediated tumor promotion." (PMID 38554152, 2024). "Consistently, PLIN3 knockdown in tumor cells not only reduced LD deposits and tumor migration, but benefited for CD8+ T cells activation in co-culture system with decreased B7-H2." (PMID 38554152, 2024). "Firstly, we evaluated the expression level of PLIN3 in normal epithelial cells and different tumor cells and found it was higher in HN6 and Cal27, but lower in Cal33." (PMID 38554152, 2024). "Histological sections showed that spotted lipid droplets-like PLIN3 staining was dominantly enriched in tumor cells (TCs) than other cell types including fibroblast-like cells (FLCs) and tumor-infiltrating lymphocytes (TILs)." (PMID 38554152, 2024). "The results indicated that patients with enhanced PLIN3+ tumor cells had relatively low ratio and numbers of CD3+ T cells and CD3+CD4+ helper/inducer T cells in blood, whereas significance was lost within immunocytes and fibroblasts." (PMID 38554152, 2024). "In our informatics analysis based on public databases, PLIN3 was highly expressed in HCC tumor tissues, and positively correlated with the tumor grade and stage of HCC patients, while the expression pattern of PLIN2 was completely opposite." (PMID 37464334, 2023). "Immunohistochemical analyses in a large number of specimens of multiple cancers demonstrated a positive correlation between PLIN3 staining intensity and tumor size in colorectal cancer, as well as tumor grade and stage in lung cancer." (PMID 36439875, 2022). "Taken together, these results indicated that ACSS3 mediated tumor suppression through PLIN3-dependent signaling." (PMID 33391508, 2021). "TG and cholesterol assay kits were used to measure TG and cholesterol contents, and Western blotting was used to measure the expression of ACSS3 and PLIN3 in tumor cells." (PMID 33391508, 2021). "C4-2 cells with stable overexpression of ACSS3 and/or knockout of PLIN3 were implanted subcutaneously or into the tail veins of immunodeficient mice to monitor tumor growth and metastasis." (PMID 33391508, 2021). "The results showed that ACSS3 inhibited cell proliferation and migration, decreased LD deposit size and promoted ER stress, and the ACSS3-mediated tumor cell suppression function was mediated through downregulation of PLIN3." (PMID 33391508, 2021). "In the current study, we found that ACSS3/PLIN3-mediated LD elimination significantly reduced lipid/cholesterol contents in tumor cells, thus repressing intratumoral androgen synthesis, thereby inhibiting CRPC progression and Enzalutamide resistance." (PMID 33391508, 2021). "Next, the expression of ACSS3, PLIN3 and Ki67 in tumor tissues was detected by IHC staining, and TUNEL assays were performed to detect tumor cell apoptosis." (PMID 33391508, 2021). "ACSS3 inhibited tumor growth and metastasis in the presence of endogenous PLIN3, while the effects of ACSS3 expression was mediated through downregulation of PLIN3." (PMID 33391508, 2021). "Furthermore, a significant association was found between elevated levels of DGAT1, DGAT2, PLIN2, PLIN3, and TG and malignancy, especially in advanced tumor stages, underscoring their promise as therapeutic targets in OC." (PMID 41041279, 2025). "However, the potential interactions between PLIN3 and other main components of the tumor microenvironment (TME), especially immunocytes in OSCC, are yet to be elucidated." (PMID 38554152, 2024).